TNF (tumor necrosis factor)
Diseases named in the same sentence as TNF in open-access papers (continued):
Sharing a sentence is not in itself a finding about the gene and the disease.
psoriasis (continued). "Thus, the first purpose of this study was to evaluate the effects of modified lipoproteins in psoriasis-like mouse and TNF-α-stimulated keratinocytes." (PMID 30177636, 2018). "In the complex immunopathology of psoriasis, it is thought that during innate immune activation, plasmacytoid dendritic cells (pDCs) are activated together with IL-1β and TNF-α producing keratinocytes in response to dendritic Toll-like receptor activation by DNA (LL-37)." (PMID 29713318, 2018). "Indeed, patients with anti-TNF induced paradoxical psoriasis showed an increased IFN signature in lesional skin." (PMID 30555460, 2018). "In our previous study, we have demonstrated that four‐cycle treatment of anti‐TNF‐α monoclonal antibody (IBI303) could reverse psoriasis through dual inhibition of inflammation and angiogenesis." (PMID 29193791, 2018). "CD patients with psoriasis or those who develop anti-TNF induced psoriasis may be the ideal candidates for ustekinumab therapy." (PMID 29980848, 2018). "Given the increased IFNA2 expression in anti-TNF-induced paradoxical psoriasis, we investigated whether TNF blockade would enhance IFN-α production by pDCs directly." (PMID 29295985, 2018). "In fact, other studies have demonstrated that several CARMA2sh variant, including Arg820Trp, could significatively affect the response to anti-TNFα treatment in psoriasis patients, with interesting implications for optimal therapy settings." (PMID 30319628, 2018). "We have confirmed that TNF‐α monoclonal antibody IBI303 could achieve good effects in the treatment of psoriasis by anti‐inflammation and inhibiting angiogenesis." (PMID 29193791, 2018). "The role of TNF-α in psoriasis immunopathological processes has already been established." (PMID 29696068, 2018). "Importantly, anti-TNF-α therapy was found to be an effective treatment for psoriasis, which provided proof for the involvement of proinflammatory mediators in promoting cutaneous inflammation in these patients." (PMID 29538330, 2018). "TNF-α, an inflammatory cytokine involved in the pathogenesis of several inflammatory diseases including psoriasis, could be inhibited by thalidomide and its derivatives such as 2-(1-benzyl-2,6-dioxopiperidin-3-yl)isoindoline-1,3-dione (4a)." (PMID 30301277, 2018). "Interestingly, natural cytotoxicity receptor positive ILC3 levels correlate with psoriasis severity in untreated patients and decrease with anti-TNF-α therapy." (PMID 30109481, 2018). "Similarly, 27% of patients with psoriasis discontinue anti-TNF treatment after a year or lose its efficacy over time." (PMID 29760711, 2018). "While TNF controls type I IFN under steady-state conditions, anti-TNF treatment may tip the balance toward type I IFN ultimately driving the psoriatic phenotype in paradoxical psoriasis." (PMID 29295985, 2018). "Activated macrophages in adipose tissue stimulate adipocytes to secrete inflammatory mediators such as TNF-α, IL-1, IL-6, and IL-8 which may account for some of the pathologic changes observed in psoriasis patients." (PMID 29680995, 2018). "A central role in the pathogenetic mechanisms involved in psoriasis is played by TNF-α." (PMID 29619128, 2018). "RA and psoriasis, other TNF mediated diseases, are also therapeutic targets of VNS." (PMID 32232080, 2018). "While observational data in large payer-based or veterans association-based cohorts suggest a reduced risk for MACEs primarily with anti-TNF agents, no trials assessing direct cardiovascular effects of these medications in psoriasis patients exist to date." (PMID 29910818, 2018). "TNF‐α inhibitors are highly effective for the treatment of psoriasis." (PMID 29193791, 2018). "Yet important immunological side effects of TNF blockade, such as paradoxical psoriasis and lupus-like syndrome, may require premature discontinuation of an otherwise effective treatment option for patients." (PMID 30555460, 2018).
psoriasis (continued). "Intriguingly, lower dose of IL‐35 could achieve a therapeutic effect similar to what TNF‐α monoclonal antibody did in psoriasis (about a total of 50 μg hIL‐35 compared to 3.75 mg IBI303 per mouse)." (PMID 29193791, 2018). "However, more surprisingly, anti-TNF treatment can also induce new psoriasis-like skin lesions in about 2–5% of treated patients." (PMID 30555460, 2018). "Besides upstream regulation of IL-23, TNF-α can act synergistically with IL-17A on epidermal keratinocytes, resulting in overexpression of various psoriasis-related proinflammatory gene including S100A7, IL-8, DEFB4, CCL20 and CXCL1." (PMID 29232931, 2017). "Moreover, some MAO inhibitors have been found to be clinically effective for skin diseases such as psoriasis and atopic dermatitis by lowering the levels of TNF-α." (PMID 28404919, 2017). "Systemic forms of treatment for psoriasis include ultraviolet light phototherapy, immunosuppressive agents (methotrexate, cyclosporine), oral retinoid (acitretin), fumaric acid esters, and biological agents (TNF-α inhibitors)." (PMID 29065479, 2017). "A further link between FABP4 and psoriasis may be a correlation with tumor necrosis factor-α (TNF-α), which is one of the major cytokines involved in the pathogenesis of this dermatosis." (PMID 27864793, 2017). "To address whether this is associated with systemic inflammatory response we performed gene-set enrichment analysis on global gene expression data from PBMCs obtained from psoriasis patients compared against TNF and IFN-γ stimulated healthy control PBMCs." (PMID 29062018, 2017). "At last, a treatment with ustekinumab (human monoclonal antibody directed against IL-12 and IL-23p40) or infliximab (monoclonal chimeric antibody directed against TNF), both used to treat psoriasis, in severe psoriatic patients appeared to decrease the activity of neutrophils and monocytes." (PMID 29249871, 2017). "We describe the case of a patient with PsA as well as poorly controlled T2DM who experienced not only improvement in his psoriasis and arthritis with the anti-TNF-α agent etanercept but also recurrent hypoglycemia and normalization of his HbA1c off of all conventional therapies for diabetes." (PMID 29721512, 2017). "Interestingly, using a bioinformatics approach of human skin and vascular tissue, IFN-γ and TNF have been determined to be the dominant pro-inflammatory signals linking atherosclerosis and psoriasis." (PMID 29295598, 2017). "TNF inhibitors are highly effective in targeting different disease features, not only with regard to axial disease and peripheral arthritis but also enthesitis and extra-articular characteristics such as psoriasis or uveitis." (PMID 28420081, 2017). "TNF-α released by multiple types of cells, including activated macrophages, dendritic cells, Th1/Th17 cells, cytotoxic T cells and adipocytes, in the serum of patients with psoriasis is essential for the progression of psoriasis." (PMID 29358932, 2017). "In addition to its proinflammatory effects, the pivotal effects of TNF-α on the pathogenesis of psoriasis are exerted through the regulated production of IL-23 from DCs." (PMID 29232931, 2017). "Moreover, treatment with TNF-α inhibitor can result in the reduced expression of IL-17 and IL-22 on the lesional psoriatic skin in patients with psoriasis." (PMID 29232931, 2017). "Most studies included in a 2014 meta-analysis showed that TNF inhibitors improve physiologic measures of endothelial function in psoriasis and psoriatic arthritis, but the evidence is somewhat contradictory, especially as regards the long-term effects of treatment." (PMID 29295598, 2017). "We report the case of a patient with PsA whose treatment with the anti-TNF-α agent, etanercept, resulted not only in improvement of his psoriasis and inflammatory arthritis but also in recurrent hypoglycemia and ultimately near normalization of his HbA1c off of all traditional therapy for T2DM." (PMID 29721512, 2017).
psoriasis (continued). "Moreover, IL-22 induces psoriasis like skin changes and its blockade can be as effective as anti-TNF in a psoriasis model." (PMID 29163483, 2017). "Treatment of psoriasis patients with TNF-α inhibitors may also have beneficial effects on the development of atherosclerosis and components of the metabolic syndrome." (PMID 29065479, 2017). "Furthermore, recent studies have reported that TNF-alpha inhibitors therapy exacerbated psoriasis or induced new onset of psoriatic skin lesions in some cases." (PMID 28761880, 2017). "However, the same conclusion has been found in a small group of patients treated for psoriasis where 1.08% developed TB despite of prophylactic screening before initiation of TNF-α inhibitor." (PMID 29104241, 2017). "Moreover, the LTBI rate in our study was 13.4% (18/134), similar to previous studies: 12/110 (11%) and 10/101 (10%) in Taiwan among TNF-blockers users for psoriasis." (PMID 28886099, 2017). "Importantly, we show that both IFN-γ and TNF-α are increased in the serum of patients with moderate-to-severe psoriasis and that their respective receptors in atherosclerotic plaques are increased." (PMID 29062018, 2017). "Although its introduction (together with other anti-tumor necrosis factor (TNF) medications) has majorly advanced psoriasis care, some patients experience persistent disease activity (primary non-responders), treatment failure over time (secondary non-responders), or side effects." (PMID 28148280, 2017). "Experiences of other authors imply that discontinuance of anti-TNF agents may result in exacerbation of the primary condition, and topical treatment is sufficient to control secondary psoriasis in most cases." (PMID 28905102, 2017). "Moreover, these immune cells release growth factors, chemokines, and pro-inflammatory cytokines such as tumor necrosis factor (TNF)-α, interleukin (IL)-6, IL-1β and IL-17, which interact as a network in the pathogenesis of psoriasis." (PMID 29295585, 2017). "There seems to be a genetic predisposition to secondary psoriasis as well, since the vast majority of patients receiving anti-TNF treatment do not develop skin lesions." (PMID 28905102, 2017). "On the other hand, a number of studies have shown that treatment with TNF-α inhibitors may lead to increased body weight and BMI in patients with psoriasis." (PMID 29065479, 2017). "In the current study, we found that it could regulate the production of TNF-α, IL-8, IL-23 and ICAM-1 associated with psoriasis." (PMID 28464025, 2017). "Furthermore, patients with psoriasis who received anti-TNF-α agents showed decreased amount of peripheral blood endothelial and platelet microparticles." (PMID 29065479, 2017). "Patients treated with anti-TNF therapy were also reported for increased risk for demyelinating disorders, like multiple sclerosis, optic neuritis, and acute transverse myelitis; paradoxical psoriasis consisting of severe skin lesions was observed in IBD patients treated with anti-TNF agents." (PMID 28083070, 2016). "TNF antagonists have proven to be highly effective for the treatment of psoriasis." (PMID 26573299, 2016). "We found that anti-TNF-α drugs also modify monocyte subsets in patients with psoriasis." (PMID 27936119, 2016). "In severe psoriasis, there was an increase of endothelial- and platelet- microparticles which could be decreased by anti-TNFα." (PMID 27144162, 2016). "There is also a reported superior clinical effect compared with etanercept, suggesting that IL-23 may have a more prominent role than TNFα in psoriasis pathogenesis." (PMID 26573299, 2016). "TNF inhibitors have shown to work well in PsoA for axial and peripheral arthritis and the other manifestations of the disease such as cutaneous lesions of psoriasis, enthesitis and dactylitis." (PMID 27338143, 2016).
psoriasis (continued). "Therefore, we applied WGCNA to coding genes and lncRNAs sequenced by RNA-seq on lesional skin samples from psoriasis patients before (PP) and after treatment (PT) with a TNF-α inhibitor, adalimumab, and on healthy control skin (NN)." (PMID 27793094, 2016). "A recent study revealed that NRIP1 may stimulate the activity of NF-κB by forming a trimeric complex with RelA and CBP, and upregulate downstream inflammatory genes, including TNF-α and IL-6, both of which play crucial roles in the pathogenesis of psoriasis." (PMID 27708240, 2016). "Findings at these time points reveal genes that may be important in the pathogenesis of psoriasis as well as direct or indirect targets of anti-TNF-α agents." (PMID 28005985, 2016). "Although indicated for the treatment of psoriasis, anti-TNF may paradoxically trigger a psoriasiform condition." (PMID 28300922, 2016). "In these trials, treatments with secukinumab and ixekizumab, anti-IL-17 monoclonal antibodies, and brodalumab, an IL-17RA receptor antagonist, indicate IL-17 inhibitors as superior in psoriasis efficacy compared to TNFα inhibitors and IL-12/IL-23 inhibitors with very few serious adverse events." (PMID 27595115, 2016). "Attenuation of CXCL10 levels is a consequence of therapies currently approved for the treatment of psoriasis and PsA, such as the phosphodiesterase-4 inhibitor apremilast and the TNFα inhibitor etanercept, further supporting a role for CXCL10 in the pathogenesis of PsA." (PMID 27964744, 2016). "TNFα is known to promote autoimmune inflammation in the skin, including psoriasis." (PMID 31051015, 2016). "In Germany the TNF antagonists adalimumab, etanercept and infliximab and the interleukin 12/23 antagonist ustekinumab have been at hand for treatment of moderate-to-severe psoriasis and psoriatic arthritis during the last years." (PMID 26633680, 2015). "The IL-17A, IL-23, and TNF-α also revealed over-expression in this psoriasis-like skin model." (PMID 26355594, 2015). "Four SNPs were associated with significant decreases in the risk of type I psoriasis (N = 155) compared with type II psoriasis (N = 36), namely, rs191190 (TNFR1; 126.08-fold), rs361525 (TNF-α; 190.76-fold), and rs10499194 and rs6920220 (TNFAIP3; 155.02-fold and 19.14-fold, resp)." (PMID 26613086, 2015). "The TNF-α treatment of human keratinocytes in vitro can induce inflammatory responses in psoriasis." (PMID 25915746, 2015). "In this study we investigated whether the red light united blue light irradiation, in combination with low concentrations of curcumin, could efficiently attenuate TNF-α-induced dermatitis, which analogous to human psoriasis lesions." (PMID 26382065, 2015). "It is possible that her psoriasis and psoriatic arthritis were triggered by treatment, though this appears unlikely because hydroxychloroquine exposure ended years before symptom onset and TNF inhibition was instituted only subsequently." (PMID 25774101, 2015). "In addition, the effects of anti-TNF-α treatment upon sphingolipid metabolism, and specifically S1P levels, in severe psoriasis patients were examined." (PMID 26174087, 2015). "The role of TNFα and IL-17 in psoriasis pathogenesis is well documented." (PMID 26556603, 2015). "Finally, slanDC, another inflammatory DC subset found in psoriasis, also induce the release of IL-1β, IL-6, TNF, IL-12, and IL-23 in response to LL37/self-RNA complexes." (PMID 26229971, 2015). "Moreover, there is evidence that TNF antagonists have a beneficial effect on preventing the progression of subclinical atherosclerosis and arterial stiffness in patients with psoriasis and inflammatory arthritis." (PMID 26633680, 2015). "The effects of adenosine, which acts through its receptors on Tcell, on mast cell and macrophages, on endothelial cells, on neutrophilsand dendritic cells, as they indicate TNF-alpha and cytokines, show thatthis mediator has a central role in the pathogenesis of psoriasis." (PMID 26734868, 2015).
psoriasis (continued). "In addition, levels of circulating sphingolipids were determined in 16 of the severe psoriasis patients after 12 weeks of treatment with the anti-TNF-α drug Etanercept." (PMID 26174087, 2015). "Since serum TNF-α is increased in active psoriasis and correlates with disease severity, higher levels of its downstream cytokines, IL-6 and IL-8, in thick plaque psoriasis likely reflects more biologic activity of TNF-α in thick plaque psoriasis." (PMID 26176783, 2015). "Finally, we found that SRSF1 levels were downregulated after patients with psoriasis were treated with anti-inflammatory agents, including a TNFα inhibitor." (PMID 25658361, 2015). "Induction of CXCL8 and TNF-α by resistin in monocytes population in blood is also linked with psoriasis pathophysiology and TNF-α stimulates keratinocyte proliferation and T cells recruitment to the skin, thus a close relationship between resistin and TNF-α-mediated inflammation exists in psoriasis." (PMID 25980409, 2015). "Recent reports show that anti-TNFα therapy may also target IL-23 and IL-17 pathway in clearing psoriasis." (PMID 25301671, 2015). "To test whether inhibition of TNF-α could suppress SRSF1 expression in patients with psoriasis, we collected PBMCs from patients at weeks 0 and 12 after treatment with adalimumab." (PMID 25658361, 2015). "Many of the upregulated genes that are involved in signaling pathways, including the IFN-γ, IL-17, and TNF signaling pathways, might be central to the pathogenesis of psoriasis." (PMID 26362816, 2015). "However, depletion of both TNF and NF-κB2 completely prevent the psoriasis-like inflammation in the Traf2EKO mice." (PMID 26701909, 2015). "Activated macrophages in the adipose tissue stimulate adipocytes to secrete adipocytokines (adipokines), such as TNF-α, IL-6, leptin, and visfatin, which may also play a role in the pathogenesis of psoriasis." (PMID 25713604, 2014). "Likewise, psoriasis is induced by TNFα blockers, although these therapies are very effective in the treatment of the skin disease." (PMID 24991219, 2014). "Multiple studies have demonstrated that BA treatment significantly decreases VEGF, MCP-1 and TNF-α in different animal model such as in LPS-challenged ApoE mice, in a transgenic model of psoriasis, in an orthotopic nude mouse model of PaCa and in a murine sponge model." (PMID 24941000, 2014). "Both erucin and sulforaphane were shown to be involved in the prevention and in the therapy of psoriasis and inflammatory skin diseases through the down-regulation of psoriasis-related cytokines, interleukin (IL)-12/23p40, IL-6 and tumor necrosis factor (TNF)-α." (PMID 24736897, 2014). "Dermatologists should be aware that patients with psoriasis both on anti-TNF therapies and insulin for diabetes may experience hypoglycemia." (PMID 25713604, 2014). "It seems that inflammatory mediators may be involved in insulin resistance, such as TNF-α, Il-6, leptin, adiponectin, mediators that are also disturbed in psoriasis (further detailed below)." (PMID 25713604, 2014). "We found 12 publications regarding the new onset of DM or PM in patients treated with anti-TNF-α agents for RA (17 cases), Crohn's disease (1 case), ankylosing spondilytis (AS, one case), and seronegative arthritis with a familiar history of psoriasis (1 case)." (PMID 24600322, 2014). "Il-1, Il-6 and TNF-α that mediate psoriasis may alter the hepatocyte function and the arterial smooth muscle cells, which will finally lead to arterial plaque development." (PMID 25713604, 2014). "Additionally, DKO* mice exhibit molecular parallels to human psoriasis, specifically a similar global protein expression pattern, complement activation, and increased TNF-α shedding." (PMID 25216727, 2014). "Changes in TNF-α levels with the duration of psoriasis could provide more definitive answer to hyperlipidemia in patients with long term psoriasis." (PMID 27433517, 2014).